CUL4B (cullin 4B)
Diseases named in the same sentence as CUL4B in open-access papers (continued):
Sharing a sentence is not in itself a finding about the gene and the disease.
X-linked intellectual disability (9 papers, 2012 to 2025). An X-linked intellectual deficiency in which not enough information is known, reported or published to indicate whether a gene causes non-syndromic or syndromic presentations. "Mutation in CUL4B gene is one of the most common causes for X-linked intellectual disability (XLID)." (PMID 38331954, 2024). "CUL4B has been identified as important regulators in cancer, X-linked intellectual disability and acute inflammatory diseases like peritonitis." (PMID 39695153, 2024). "The deletion of GRIA3 and CUL4B genes are the cause of X-linked mental retardation or/and X-linked intellectual disability." (PMID 36329552, 2022). "In this study, we demonstrate that an E3-ubiquitin ligase associated with human X-linked intellectual disability, CUL4B, plays a crucial role in post-meiotic sperm development." (PMID 26832838, 2016). "It has been shown recently that mutations of another ubiquitin ligase cullin-4b (cul4b) in the X chromosome cause X-linked intellectual disability (XLID) in males." (PMID 22992378, 2012). "Mutation in CUL4B gene is one of the top causes of human X-linked intellectual disability." (PMID 39695153, 2024). "A major part of this complex is CUL4B, whose mutations cause X-linked intellectual disability." (PMID 32668698, 2020). "Genetic mutations of cullin-4b (cul4b) cause a prevalent type of X-linked intellectual disability (XLID) in males, but the physiological function of Cul4B in neuronal cells remains unclear." (PMID 22992378, 2012). "The mutations in the CUL4B gene are revealed to be a cause of Cabezas syndrome (OMIM 300354), a rare syndromic form of X-linked intellectual disability (XLID)." (PMID 40761315, 2025). "Cabezas syndrome (OMIM 300354), a rare syndromic form of X-linked intellectual disability (XLID), was revealed to be caused by CUL4B mutations." (PMID 40761315, 2025).
ovarian carcinoma (7 papers, 2020 to 2025). A malignant neoplasm originating from the surface ovarian epithelium. "CUL4B is an independent risk factor for overall survival and disease-free survival in ovarian cancer." (PMID 35909905, 2022). "The results showed that the expression of Cul4B in human ovarian cancer was significantly associated with patient disease-free survival and overall survival." (PMID 32622365, 2020). "Cul4B expression was associated with FIGO stage and Cul4B was independent risk factor of ovarian cancer disease-free survival and overall survival." (PMID 32622365, 2020). "The results revealed that high expression of Cul4B is associated with poor ovarian cancer prognosis and Cul4B may serve as a potential treating target for an adjuvant therapy." (PMID 32622365, 2020). "Altered expression of CUL4B has been reported in various types of cancer, including breast, lung, liver, and ovarian cancers." (PMID 37888480, 2023). "In vitro explorations have shown that CUL4B overexpression promotes tumor proliferation, while CUL4B knockdown significantly inhibits the proliferation of ovarian cancer cells." (PMID 35909905, 2022). "In ovarian cancer, CUL4B was overtly up-regulated in cancer tissues and CUL4B facilitated cancer cell proliferation by mediating CDK2 and CyclinD1." (PMID 33292255, 2020). "We first examined cell cycle pattern and performed cell death analysis in control and Cul4B overexpressing ovarian cancer cells." (PMID 32622365, 2020). "The results revealed that 3′ UTR luciferase reporter activity of CDK2 and CyclinD1 was upregulated in Cul4B overexpressing ovarian cancer cells." (PMID 32622365, 2020). "In vitro studies revealed that overexpression of Cul4B promoted tumor proliferation while knockdown of Cul4B significantly inhibited the proliferation capacity of ovarian cancer cells." (PMID 32622365, 2020). "Cul4B regulates the expression of CDK2 and CyclinD1 by repressing miR-372.These results indicate a role of Cul4B in the regulation of cell cycle in ovarian cancer." (PMID 32622365, 2020). "In this study, we used immunohistochemistry to detect the expression of CUL4B in ovarian cancer and used the ovarian cancer cell lines as a model to analyze the effect of Cul4B on the proliferation of ovarian cancer cells." (PMID 32622365, 2020). "Cul4B overexpression reduced the proportion of G0/G1 phase and increased the proportion of S phase, these results revealed that Cul4B promoted ovarian cancer cells entering S phase from G0/G1 phase." (PMID 32622365, 2020). "Knockdown of circ_0015756 suppressed OC progression via regulating miR-942-5p/CUL4B axis, suggesting that circ_0015756 might be a potential therapeutic target for ovarian cancer." (PMID 33292255, 2020). "The purpose of this study is to investigate the role of Cul4B in the progression of ovarian cancer." (PMID 32622365, 2020). "First, the expression of Cul4B in human ovarian cancer was detected by immunohistochemistry." (PMID 32622365, 2020). "We also examined whether Cul4B regulates the expression of miR-372 in ovarian cancer." (PMID 32622365, 2020). "We also found that CUL4B dependency was specific to HRD cell lines in breast and ovarian cancer types." (PMID 39485057, 2024). "Cell apoptosis analysis reveal no different in cell apoptosis between control cells and Cul4B overexpressing cells which means that Cul4B does not affect ovarian cancer cell apoptosis." (PMID 32622365, 2020). "We then examined whether Cul4B upregulates the expression of CDK2 and CyclinD1 by repressing miR-372 in ovarian cancer." (PMID 32622365, 2020). "There is no report on whether expression of Cul4B in the intratumor tissue affects ovarian cancer patient survival, we analyzed the expression of Cul4B in the tumor tissue by immunohistochemistry staining analysis." (PMID 32622365, 2020). "However, the role of CUL4B in ovarian cancer has not been reported." (PMID 32622365, 2020). "However, the role of Cul4B in ovarian cancer has not been studied." (PMID 32622365, 2020).
ovarian carcinoma (continued). "However, up to now, the role of Cul4B in ovarian cancer has not been reported." (PMID 32622365, 2020).
pancreatic cancer (6 papers, 2019 to 2025). "Strikingly, SIRT1 and CUL4B expression is markedly upregulated in a variety of human cancers, including pancreatic cancer." (PMID 34163012, 2021). "We demonstrated that SIRT1 and CUL4B positively regulate CSC-like features in pancreatic cancer cells." (PMID 34163012, 2021). "Our findings indicated that the SIRT1/CRL4B complex functions as a whole, while co-phenotypic experiments with SIRT1 showed that CUL4B positively correlated with autophagy in pancreatic cancer." (PMID 34163012, 2021). "CUL4B induces EMT via the Wnt/beta‐catenin signaling pathway in pancreatic cancer cells." (PMID 33107222, 2021). "To further elucidate whether SIRT1 and CUL4B promote the development of pancreatic cancer cells into CSCs, repopulating from single cells, we analyzed the effect of SIRT1 and CUL4B on sphere formation." (PMID 34163012, 2021). "Furthermore, we found that SIRT1 and CUL4B collectively promote the proliferation, autophagy, and invasion of pancreatic cancer cells." (PMID 34163012, 2021). "Next, we investigated whether SIRT1 and CUL4B affect stem-like phenotypes in pancreatic cancer cells." (PMID 34163012, 2021). "Furthermore, analysis of a published clinical dataset (GSE15471) revealed that compared with normal pancreatic tissues, SIRT1 and CUL4B expression increased in pancreatic tumor samples, while FOXO3 and GRHL3 significantly decreased." (PMID 34163012, 2021). "We collected 86 pancreatic carcinoma samples from pancreatic cancer patients and performed tissue microarrays via immunohistochemical staining, to examine the expression of SIRT1, CUL4B, and FOXO3." (PMID 34163012, 2021). "SIRT1 or CUL4B knockdown in PANC-1 cells decreased cell invasion potential, which was partially rescued via the co-knockdown of FOXO3 or GRHL3, indicating that the SIRT1/CRL4B complex could promote pancreatic cancer invasion through repression of FOXO3 and GRHL3." (PMID 34163012, 2021).
prostate carcinoma (6 papers, 2019 to 2025). A carcinoma that arises from epithelial cells of the prostate gland. "Earlier, we demonstrated that CUL4B promotes prostate cancer progression by establishing a positive feedback loop with SOX4, amplifying its oncogenic effects." (PMID 40203790, 2025). "It has been reported that miR-101-3p targets CUL4B to block the PI3K/AKT/mTOR pathway in prostate cancer cells." (PMID 38532426, 2024). "Our previous research has identified an oncogenic role for CUL4B in gastric and prostate cancers." (PMID 40203790, 2025). "However, the role of CUL4B in prostate cancer remains unclear." (PMID 36969009, 2023).
Cabezas syndrome (5 papers, 2020 to 2025). "CUL4B is a haploinsufficient gene (HI score = 3), and frameshift mutations in its coding region can lead to a loss of function, thereby causing Cabezas syndrome (Thus, PVS1 applied)." (PMID 40761315, 2025). "We report a case of a 10-year-old boy with ID and GDD who was diagnosed with Cabezas syndrome, a rare genetic disorder caused by a deletion of the CUL4B gene." (PMID 37900499, 2023).
colon cancer (5 papers, 2015 to 2020). "Elevated expression of CUL4B was confirmed in colon tumors and was associated with poor overall survival." (PMID 32054830, 2020). "Furthermore, we found that elevated CUL4B expression is associated with miR34a downregulation and upregulation of miR34a target genes in colon cancer specimens." (PMID 32054830, 2020). "Cul4B was highly expressed in protein and mRNA levels in colon cancer tissues and was significantly related to the infiltration depth of tumor, lymph node metastasis, distal metastasis, tissue differentiation, vascular invasion and tumor pathological grade." (PMID 32622365, 2020). "We then tested lung metastasis of CUL4B knockdown and control colon cancer cell lines by tail vein injection." (PMID 32054830, 2020). "Inhibiting the expression of CUL4B can inhibit the proliferation of colon cancer cells and increase the proportion of apoptosis." (PMID 32622365, 2020). "In colon cancer, patients with CUL4B-positive tumors had a higher recurrence rate and shorter survival time compared to patients with CUL4B-negative tumors." (PMID 33233664, 2020). "In order to elucidate the regulation network of CUL4B in colon cancer regulation, we performed RNA sequencing of CUL4B knockdown and its control PDOs from three individuals." (PMID 32054830, 2020). "For example, Cullin-4B (CUL4B) upregulates the expression of the CSC marker CD44 to maintain colon cancer stemness and drive malignant progression to affect prognosis." (PMID 33680915, 2020). "Nevertheless, a recent work found that CUL4B overexpressed in colon cancer, and its overexpression closely related to tumor stage, histological differentiation, vascular invasion and distant metastasis." (PMID 26460955, 2015). "We thus performed miRNA sequencing in #16PDOs and identified 59 candidate miRNAs that might be regulated by CUL4B in colon cancer." (PMID 32054830, 2020). "Here, we aimed to identify the new regulators of CCSCs and found that Cullin 4B (CUL4B), which possesses oncogenic properties in multiple solid tumors, drives the development and metastasis of colon cancer by sustaining cancer stem-like features." (PMID 32054830, 2020). "Overexpression of Cul4B in SKOV-3 cell line promotes cell proliferation while knockdown of Cul4B in Hey cell line inhibits cell proliferation which is in accordance with findings in liver cancer and colon cancer." (PMID 32622365, 2020). "Thus, specific inhibitors of CUL4B could increase the level of TOP1 and consequently improve therapeutic effect of irinotecan on colon cancer." (PMID 26460955, 2015).
colorectal cancer (5 papers, 2020 to 2025). A primary or metastatic malignant neoplasm that affects the colon or rectum. "In summary, through our current study, we found that CUL4B can affect the progression and prognosis of colorectal cancer by playing a vital role in oxaliplatin resistance." (PMID 36385733, 2022). "Our study has for the first time found that CUL4B is an important target gene for resistance of platinum‐based drugs in colorectal cancer." (PMID 36385733, 2022). "CUL4B functions as a carcinogen in diverse tumors, including bladder cancer, colorectal cancer and lung adenocarcinoma." (PMID 33292255, 2020). "CUL4B leads to platinum drug resistance in colorectal cancer by affecting tumour EMT." (PMID 36385733, 2022). "And we found CUL4B increases platinum‐based drug resistance in colorectal cancer through EMT." (PMID 36385733, 2022).
hepatocellular carcinoma (5 papers, 2015 to 2025). A malignant tumor that arises from hepatocytes. "To determine the role of CUL4B in liver tumorigenesis, we generated transgenic mice that expressed human CUL4B in livers and other tissues and evaluated the development of spontaneous and chemically-induced hepatocellular carcinomas." (PMID 25945838, 2015). "To clarify the roles of CUL4B in liver tumorigenesis, we generated transgenic mice expressing human CUL4B under the control of the CMV promoter and examined the development of spontaneous and chemically-induced hepatocellular carcinomas." (PMID 25945838, 2015). "Our results show that CUL4B transgenic mice spontaneously developed liver tumors and greatly accelerated DEN-induced hepatocellular carcinoma development." (PMID 25945838, 2015).
lung adenocarcinoma (5 papers, 2017 to 2023). A carcinoma that arises from the lung and is characterized by the presence of malignant glandular epithelial cells. "Our findings revealed an oncoprotein‐RNA axis, providing novel insight into how CUL4B is activated and contributes to lung adenocarcinoma progression." (PMID 31448526, 2019). "Together, these results suggest that CUL4B is overexpressed in primary lung adenocarcinoma tissues and this increased expression is maintained in the metastatic tissues." (PMID 28164432, 2017). "We examined CUL4B protein levels in 74 paired cases of lung adenocarcinoma specimens by immunohistochemistry." (PMID 28164432, 2017). "Moreover, CUL4B levels were higher in 55 (74.32%) lung adenocarcinoma samples than in matched noncancerous tissues." (PMID 28164432, 2017).
male infertility (5 papers, 2016 to 2024). The inability of the male to effect fertilization of an ovum after a specified period of unprotected intercourse. "The conditional removal of Cul4b in germ cells results in male infertility associated with asthenozoospermia and teratozoospermia due to impaired spermiogenesis." (PMID 34685710, 2021). "Disruption of Cul4A in mice resulted in male infertility due to abnormal meiotic progression, whereas disruption of Cul4B in mice caused male infertility because of aberrant post-meiotic sperm development." (PMID 29907856, 2018). "Indeed, the CUL4 E3 ubiquitin ligase plays a central role in mammalian spermatogenesis, as shown by male infertility observed in null mutations of the Cul4A or Cul4B genes in mice." (PMID 37689310, 2023). "Defects in any of these pathways would cause male infertility, thereby supporting the hypothesis that CUL4B is critical for coordinating the structural factors that are required for subcellular organelle transformation and survival in the initial post-meiotic spermatids." (PMID 26832838, 2016). "For example, the knockout of CUL4B in mice results in male infertility because it disrupts the preservation of the spermatogonial stem cell environment." (PMID 39866841, 2024). "In our previous study, we have reported that germ-cell specific removal of Cul4b (Cul4bVasa) led to male infertility due to spermiogenesis defects, whereas global Cul4b knockout mice (Cul4bSox2) exhibited an age-dependent germ-cell depletion phenotype." (PMID 34685710, 2021). "Collectively these data demonstrate that genetic removal of Cul4b in both germ cells and Sertoli cells led to male infertility phenotypically distinct from that of the Cul4bAmh and Cul4bVasa single knockout, as well as that of the global Cul4b null mutants." (PMID 34685710, 2021). "Whereas, the male infertility phenotype resulted from Cul4B deletion was due to abnormal post-meiotic sperm development." (PMID 29907856, 2018). "Our results enhance the understanding of the molecular basis of CUL4B in spermiogenesis, and they have the potential to facilitate the development of non-hormonal male contraceptives and therapeutic strategies to treat male infertility." (PMID 26832838, 2016).
X-linked mental retardation syndrome (5 papers, 2009 to 2023). "CUL4B was recently identified as a causative gene for an X-linked mental retardation syndrome, which was associated with several clinical features, including central obesity." (PMID 19461885, 2009). "Furthermore, DHX30 forms an interaction with CUL4B, which is associated with X-linked intellectual disability syndrome." (PMID 38025430, 2023). "In addition, mutations in CUL4B are linked to an X-linked mental retardation syndrome in man and Cul4B−/− mice display embryonic lethality due to developmental failure of extra-embryonic tissues." (PMID 25833379, 2015). "Mutations of CUL4B located on chromosome Xq24 are associated with X-linked mental retardation syndrome, but its mutation has not been yet reported in cancers, including MPM." (PMID 33233664, 2020).
bladder cancer (4 papers, 2020 to 2023). "In addition, Cullin 4B has been found to promote EMT and metastasis by upregulating the Wnt/β-catenin pathway in bladder cancer." (PMID 33423167, 2021).
cervical carcinoma (4 papers, 2017 to 2022). A carcinoma arising from either the exocervical squamous epithelium or the endocervical glandular epithelium. "Cullin4B (CUL4B) is an E3 ubiquitin ligase that is associated with tumorigenesis and is overexpressed in human cervical cancer." (PMID 35159030, 2022). "In cervical carcinoma, CUL4B expression has been shown to be linked to histological grades with high expression related to tumor size, invasion, and metastasis." (PMID 29594129, 2018). "Overexpression of CUL4B in several cancers such as lung, colon, pancreatic, esophageal, liver, kidney, bladder, and cervical cancer, generally associated with poor patient prognosis, has been reviewed elsewhere recently." (PMID 29594129, 2018). "This study suggests that CUL4B enhances the proliferation and invasion of cervical cancer by repressing its target genes." (PMID 35159030, 2022). "In the past, DNMT3a has been shown to epigenetically regulate the levels of IGFBP3 in cervical cancer by CUL4B;15 DNMT3a deprivation in liver cancer results in an increased IGFBP3 expression." (PMID 28393842, 2017).
non-small cell lung carcinoma (4 papers, 2019 to 2022). A group of at least three distinct histological types of lung cancer, including non-small cell squamous cell carcinoma, adenocarcinoma, and large cell carcinoma. "In non-small cell lung cancer and prostate cancer, CUL4B is confirmed as a functional target of miR-101, and its knockdown results in a strong alleviation of cell proliferation, which is enhanced by the silencing of miR-101." (PMID 36497343, 2022). "When Cul4b was knocked down in colorectal and non-small cell lung cancer cell lines, both cell proliferation and invasion were suppressed, concomitant with the inhibition of positive cell cycle regulators, including cyclin D1." (PMID 31260508, 2019). "In addition, circ_0072083 could promote cell proliferation, migration and invasion via regulating miR-101-3p/cullin 4B (CUL4B), and facilitated cisplatin resistance via regulating miR-545-3p/Cbl proto-oncogene like 1 (CBLL1) in non-small cell lung cancer." (PMID 33975615, 2021).